LRP5 (LDL receptor related protein 5)
Diseases named in the same sentence as LRP5 in open-access papers (continued):
Sharing a sentence is not in itself a finding about the gene and the disease.
osteoporosis-pseudoglioma syndrome (49 papers, 2010 to 2025). Osteoporosis pseudoglioma syndrome is a very rare autosomal recessive disorder characterized by congenital or infancy-onset blindness and severe juvenile-onset osteoporosis and spontaneous fractures. "Humans who are homozygous for inactivating mutations in LRP5 develop osteoporosis pseudoglioma (OPPG), a syndrome characterized by bone and eye abnormalities." (PMID 40932232, 2025). "Most of them cause known monogenic disorders, such as osteogenesis imperfecta (COL1A1/COL1A2), pycnodysostosis (CTSK), X-linked osteoporosis (PLS3), osteopetrosis, X-linked hypophosphatemia (PHEX), and osteoporosis pseudoglioma syndrome (LRP5)." (PMID 37731773, 2023). "For example, total loss-of-function variants of LRP5 were found to be the cause of osteoporosis-pseudoglioma syndrome (OPPG)." (PMID 37895195, 2023). "Loss-of-function LRP5/6 mutations were identified in osteoporosis pseudoglioma (OPPG) patients, a disease characterized by thinning of the bones and impaired vision." (PMID 35600583, 2022). "Of note, AFF occurred in one case of osteoporosis pseudoglioma syndrome associated with two novel compound heterozygous mutations in LRP5." (PMID 35052486, 2022). "The importance of these transmembrane co-receptors in bone was revealed by the description of mutations in LRP5 that caused two diametrically opposed bone phenotypes: osteoporosis pseudoglioma syndrome (OPPG), and the high bone mass (HBM) phenotype." (PMID 35052478, 2022). "In 2001, low-density lipoprotein receptor-related protein 5 (LRP5) was identified as a causative gene for osteoporosis pseudoglioma syndrome (OMIM: 258770) and functions as a Wnt co-receptor to promote bone accrual by enhancing Wnt/β-catenin signals." (PMID 35563281, 2022). "Mutation in the LRP5 gene was firstly identified in osteoporosis pseudoglioma syndrome, an autosomal recessive disease characterized by severe osteoporosis revealing in infancy and associating with a congenital blindness." (PMID 34948434, 2021). "More specifically, homozygous loss-of-function mutations in LRP5 can cause the osteoporosis-pseudoglioma (OPPG) syndrome which is characterized by reduced bone mass, increased bone fragility, and severely reduced visual acuity." (PMID 32328030, 2020). "Lrp5-deficient mice have increased Tph1 and in humans, mutation in the Lrp5 gene causes osteoporosis pseudoglioma, which is characterized by bone loss and blindness." (PMID 32933099, 2020). "Mutation of LRP5 can cause osteoporosis pseudoglioma syndrome (OPPG) in humans and decrease osteoblast numbers in mice." (PMID 32012654, 2020). "A reduction in canonical Wnt signalling is associated with low bone mineral density in patients with osteoporosis pseudoglioma syndrome that exhibit a loss of function mutation in LRP5 and increased bone is observed in activating LRP5 mutations." (PMID 30287279, 2019). "For example, certain missense mutations in LRP5 gene cause high bone mass and other conditions with increasing bone density, whereas other missense mutations in the same gene cause osteoporosis pseudoglioma syndrome." (PMID 25701875, 2015). "Recessive loss-of-function mutations that map to the Human LRP5 gene cause osteoporosis pseudoglioma (OPPG) syndrome, which is characterized by low bone mass, while a dominant gain-of-function mutation results in the High Bone Mass (HBM) trait." (PMID 24789067, 2014). "The importance of LRP5 in bone was initially established by demonstrating that inactivating mutations in this co-receptor caused osteoporosis pseudoglioma (OPPG), a rare syndrome associated with premature and generalized osteoporosis." (PMID 23675479, 2013). "For example, mutation in NDP causes either FEVR or Norrie disease (a more severe phenotype), and mutation in LRP5 causes FEVR or osteoporosis pseudoglioma syndrome, a more severe phenotype." (PMID 23441120, 2013).
osteoporosis-pseudoglioma syndrome (continued). "Specifically, loss of function mutations in the Wnt-co receptor LRP5, as seen in osteoporosis pseudoglioma syndrome, result in a dramatic loss in bone mass, while gain of function mutations give rise to extremely high BMD (5 SD above normal)." (PMID 22792071, 2012). "Clinical results have identified in human, a link between bone mass and mutations in LRP-5 with loss of function causing osteoporosis pseudoglioma syndrome and gain of function leading to pathological thickening of bone." (PMID 22666151, 2012). "Loss of function mutations in LRP5 result in osteoporosis-pseudoglioma (OPPG) primarily characterized by low bone mass." (PMID 21887268, 2011). "Inactivating mutations of the human LRP5 gene result in osteoporosis pseudoglioma syndrome, and a similar phenotype has been observed in mice with a targeted deletion of Lrp5." (PMID 20436912, 2010). "Loss of function of the Wnt co-receptor, LRP5, have been shown to lead to disorders of decreased bone mass, such as Osteoporosis Pseudoglioma Syndrome (OPS)." (PMID 20843343, 2010). "Loss-of-function mutations in LRP5 cause osteoporosis-pseudoglioma syndrome (OPPG), a low bone mass disorder, with severe low BMD and pathological vascularization of the retina, while point mutations having a gain-of-function affect have been observed in individuals with high bone mass." (PMID 36120446, 2022). "The low-density lipoprotein (LDL) receptor-related protein 5 (LRP5) gene, whose inactivating mutations have been associated to low bone mass in osteoporosis pseudoglioma syndrome, can be considered to be another strong candidate contributing to idiopathic osteoporosis." (PMID 34948434, 2021). "Loss-of-function mutations in Lrp5 cause the osteoporosis pseudoglioma (OPPG) syndrome." (PMID 26121341, 2015). "For example, loss-of-function mutations in LRP5 have been reported to cause the autosomal recessive human disease osteoporosis-pseudoglioma syndrome (OPPG), which leads to significant reduction of BMDs, and are more susceptible to skeletal fracture and deformity." (PMID 25215295, 2014). "LRP5 is one of the most intensively studied regulators of bone remodeling, largely because Lrp5 loss-of-function mutations cause the autosomal recessive human disorder osteoporosis-pseudoglioma syndrome (OPPG), whereas activating mutations in Lrp5 cause high bone mass syndrome." (PMID 24479426, 2014). "Osteoporosis-Pseudoglioma Syndrome (OPPG) is an autosomal recessive disorder and is caused by homozygous pathogenic variants in LRP5, due to the receptor function as a key regulator of bone metabolism through the Wnt signaling pathway." (PMID 38244079, 2024). "Human mutations in LRP5 and SOST (sclerostin) alter WNT signaling and cause osteoporosis-pseudoglioma syndrome (OPPG) and van Buchem disease." (PMID 36814601, 2023). "In addition, the mutations in LRP5 cause osteoporosis-pseudoglioma syndrome (OPPG) autosomal disorder." (PMID 36839380, 2023). "LRP5 is a well-known regulator of BMD and gain and loss of function mutations lead to high bone mass syndrome and osteoporosis pseudoglioma, respectively." (PMID 36416764, 2022). "Osteoporosis-Pseudoglioma Syndrome (OOPG) is a very rare AR condition, with around 50 cases reported, caused by loss of function mutations in the LRP5 gene." (PMID 31888683, 2019). "Osteoporosis-pseudoglioma (OPPG) syndrome is a very rare autosomal recessive disorder, caused by mutations in the low-density lipoprotein receptor-related protein 5 (LRP5) gene." (PMID 26904320, 2016). "Osteoporosis-pseudoglioma (OPPG), an autosomal recessive disease characterized by bone thinning and blindness due to abnormal eye development has been linked to loss of function mutation in LRP5." (PMID 27582019, 2016). "For instance, the inactivation of LRP5 leads to osteoporosis-pseudoglioma syndrome (OPPG)." (PMID 39980864, 2025).
osteoporosis-pseudoglioma syndrome (continued). "While Lrp5 does not directly promote bone loss, its regulation of GDS levels impacts bone homeostasis in patients with osteoporosis pseudoglioma." (PMID 32933099, 2020). "Osteoporosis-pseudoglioma syndrome (OPPG; OMIM #259770) is less common disease, this disease is related to the LRP5." (PMID 38355430, 2024).
Familial exudative vitreoretinopathy (37 papers, 2007 to 2025). Familial exudative vitreoretinopathy (FEVR) is a rare hereditary vitreoretinal disorder characterized by abnormal or incomplete vascularization of the peripheral retina leading to variable clinical manifestations ranging from no effects to minor anomalies, or even retinal detachment with blindness. "Related to OPPG is LRP5 variant-induced familial exudative vitreoretinopathy (FEVR; OMIM 133780), a disorder characterized by disorganized retinal blood vessel development leading to incomplete vascularization of the peripheral retina." (PMID 37895195, 2023). "A heterozygous loss-of-function LRP5 pathogenic variant can predispose to juvenile osteoporosis or exudative vitreoretinopathy." (PMID 37277619, 2023). "In humans, mutations in NDP, FZD4, LRP5 or TSPAN12 genes are linked to familial exudative vitreoretinopathy (FEVR), which is characterized by retinal vascular defects, vision impairment, or blindness." (PMID 28675177, 2017). "Since patients with loss-of-function LRP5 variants may develop exudative vitreoretinopathy, a disease with a highly variability in phenotypic expression, we had anticipated that those with an LRP5 variant would have more DTCs opened for ophthalmology." (PMID 37277619, 2023). "Human patients with loss-of-function variants in LRP5 can also develop familial exudative vitreoretinopathy (FEVR), a disease characterized by a paucity of blood vessels at the retinal periphery and hemorrhages of other regional blood vessels." (PMID 40932232, 2025). "Loss-of-function mutations in Norrin, FZD4, LRP5 and Tspan12 all cause familial exudative vitreoretinopathy (FEVR) in humans." (PMID 24058663, 2013). "Mutations in low-density lipoprotein receptor-related protein 5 (Lrp5) impair retinal angiogenesis in patients with familial exudative vitreoretinopathy (FEVR), a rare type of blinding vascular eye disease." (PMID 22272305, 2012). "Loss-of-function mutations in Norrin (an unconventional Wnt ligand), Wnt receptor Frizzled 4 (FZD4) or co-receptor LRP5, can cause familial exudative vitreoretinopathy (FEVR) in humans." (PMID 20652025, 2010). "Mutations in Norrin, Fzd4, LRP5, β-catenin, and Tspan12 are associated with inherited diseases of the retinal vasculature, most notably familial exudative vitreoretinopathy (FEVR), and therapeutic targeting of Norrin/β-catenin signaling shows promise for modulating the BRB and BBB." (PMID 39745873, 2025). "Similarly, in familial exudative vitreoretinopathy (FEVR), a hereditary disorder in humans characterized by inactivating mutations of LRP5, deficient peripheral retinal vascularization leads to progressive vision loss." (PMID 40940800, 2025). "In humans, two rare pediatric eye diseases, familial exudative vitreoretinopathy (FEVR) and X-linked Norrie disease, correspond to the loss-of-function mutations in Norrin/Fzd4/LRP5 axis and/or several other genes and norrin (Ndp) gene, respectively." (PMID 37887287, 2023). "Mutations in human genes NDP, FZD4, LRP5 and TSPAN12 cause familial exudative vitreoretinopathy, a potentially blinding disease initially characterized by retinal hypovascularization." (PMID 28675177, 2017). "Mutations in candidate genes that encode for a ligand (NDP) and receptor complex (FZD4, LRP5 and TSPAN12) in the Norrin β-catenin signaling pathway are involved in the pathogenesis of familial exudative vitreoretinopathy (FEVR, MIM # 133780)." (PMID 27316669, 2016). "Additionally, mutations in LRP5 have been linked to the recessive form of familial exudative vitreoretinopathy (FEVR; OMIM #601813)." (PMID 24906390, 2014). "Previous research revealed that Slc38a5 was significantly decreased in both Lrp5−/− and Ndpy/− retinas, which are experimental models of familial exudative vitreoretinopathy (FEVR) and Norrie disease, respectively, two genetic vascular eye diseases with inadequate retinal vasculature." (PMID 39335451, 2024).
Familial exudative vitreoretinopathy (continued). "Norrie's disease and familial exudative vitreoretinopathy (FEVR) are retinal conditions, which present similarly to ROP engendered, engendered by a single genetic variant many of which overlap with ROP including NDP, FZD4 TSPAN12, and LRP5 from our analysis." (PMID 37492605, 2023). "Families OFT-00178 and OFT-00332 had variants in gene LRP5 that are related to syndromes without ocular features and exudative vitreoretinopathy." (PMID 35457050, 2022). "Moreover, the p.R494WLRP5 that affects the same amino acid of LRP5 was identified as a potential pathogenic variant in a patient with Familial Exudative Vitreoretinopathy (FEVR), adding further support to the critical role of this amino acid to produce functional LRP5." (PMID 38244079, 2024). "Abnormalities in Fz4 or LRP5 result in a phenotypically similar condition, familial exudative vitreoretinopathy (FEVR) characterized by defects in retinal vascular development." (PMID 17386109, 2007). "The literature has also described the case report of a child affected by 22q11.2DS, presenting familial exudative vitreoretinopathy (FEVR), in the absence of the pathognomonic mutations LRP5 and FZD4." (PMID 39202748, 2024). "FZD4, LRP5, or TSPAN12 mutations are also the causes of a spectrum of related congenital retinopathies such as osteoporosis-pseudoglioma syndrome, familial exudative vitreoretinopathy (FEVR), and Coats disease, each of which share resembling phenotypes with Norrie disease." (PMID 36432666, 2022).
breast cancer (34 papers, 2009 to 2026). A primary or metastatic malignant neoplasm involving the breast. "We previously found that homozygosity for a null allele of Lrp5 inhibits tumor progression in the MMTV-Wnt1 mouse mammary tumor model." (PMID 40932232, 2025). "In the mouse model, Lrp5 CM suppressed the progression of mammary tumors and tumor-driven bone loss." (PMID 34976221, 2022). "We showed that the silencing of Lrp5 in EO771 mammary tumor cells suppressed tumor-induced bone loss, while Lrp5 deletion in the conditional knockout mouse model stimulated bone degradation." (PMID 34230453, 2021). "Systemic administration of CM from osteocytes with overexpression of Lrp5 or β-catenin strikingly reduced mammary tumor growth and tumor-induced bone loss." (PMID 34230453, 2021). "Of note, Lrp5 expressed in tumor cells has a protumorigenic role, as mice injected with Lrp5-silenced EO771 tumor cells showed a reduction in mammary tumor growth and tumor-driven bone loss." (PMID 34230453, 2021). "By contrast, LRP5-deficient mice are viable, but develop Wnt1-induced mammary tumors much later than control mice, suggesting that LRP6 cannot compensate for LRP5 loss." (PMID 29854300, 2018). "The results herein suggest that the regulation of Lrp5-mediated dopaminergic signaling may provide a novel strategy to restrain breast-cancer-associated tumor growth in the brain." (PMID 34031366, 2021). "Using a mouse model of bone metastasis associated with breast cancer and prostate cancer, the main question we addressed in this study was whether Lrp5 in osteocytes is necessary to induce loading-driven tumor suppression." (PMID 33450808, 2021). "Together, our results demonstrate that LRP5 in osteocytes inhibits effects on breast cancer cells primarily by activating the LIMA1/MYO5B signaling axis." (PMID 41596426, 2026). "In osteocytes, LRP5 not only mediates load-induced bone anabolism but also inhibits tumor-driven osteolysis in breast cancer models." (PMID 41596426, 2026). "In the mammary tumor model, treatment with LRP5-overexpressing osteocyte-derived CM significantly reduced tumor volume and weight compared with the control CM." (PMID 41596426, 2026). "Previous work has shown that osteocyte-specific overexpression of the Wnt co-receptor LRP5 inhibits breast cancer-induced osteolysis and generates conditioned medium (CM) with tumor-suppressive activity." (PMID 41596426, 2026). "Building on our previous observation that conditioned medium from LRP5-overexpressing osteocytes inhibits breast cancer cells, we sought to further validate the anti-tumor capacity of osteocytes." (PMID 41596426, 2026). "In summary, this study revealed that LRP5 overexpression in bone cells significantly inhibited breast cancer cell proliferation, migration, and invasion, and regulated osteoclast differentiation and immune response by activating the LIMA1/MYO5B signaling axis." (PMID 41596426, 2026). "In mouse models of breast cancer and breast cancer bone metastasis, LRP5-overexpressing osteocyte-derived CM markedly reduced tumor burden and osteolytic lesions, whereas genetic knockdown of either LIMA1 or MYO5B abolished these protective effects." (PMID 41596426, 2026). "To validate the tumor-suppressive and bone-protective effects of LRP5-overexpressing osteocyte-derived CM in vivo, we established syngeneic mammary tumor and tibial bone metastasis models in C57BL/6 mice." (PMID 41596426, 2026). "Mechanistically, RNA sequencing analysis screened out that butyrate decreases LRP5 expression to block the activation of Wnt/β-catenin signaling pathway, dampening breast cancer stemness." (PMID 40038255, 2025). "CCK8 assay showed that NaBu treatment (2 mM or 4 mM) had little effect on cell viability of breast cancer, while dose-dependently inhibited LRP5 mRNA level." (PMID 40038255, 2025). "Taken together, butyrate suppresses LRP5 expression to block Wnt/β-catenin signaling activity, reducing breast cancer stemness." (PMID 40038255, 2025).